PEPD (peptidase D)
Description:
Dipeptidase that catalyzes the hydrolysis of dipeptides with a prolyl (Xaa-Pro) or hydroxyprolyl residue in the C-terminal position. The preferred dipeptide substrate is Gly-Pro, but other Xaa-Pro dipeptides, such as Ala-Pro, Met-Pro, Phe-Pro, Val-Pro and Leu-Pro, can be cleaved. Plays an important role in collagen metabolism because the high level of iminoacids in collagen.
Synonyms: Prolidase
Tractability: Small molecule: a structure with a bound ligand is known; it has a high-quality binding pocket; it belongs to a druggable protein family. PROTAC: ubiquitination databases record sites on it; its protein half-life has been measured; a small molecule that binds it is known.
Target class: Metallo protease MG clan; Metallo protease M24B subfamily; Enzyme; Protease; Metallo protease
Gene: Protein-coding gene on chromosome 19 (33,386,950 to 33,521,823, reverse strand). Ensembl gene ENSG00000124299.
Subcellular location (Human Protein Atlas): Nucleoplasm
Gene Ontology:
Molecular function: proline dipeptidase activity; protein binding; metallocarboxypeptidase activity; manganese ion binding; metalloaminopeptidase activity; metalloexopeptidase activity; peptidase activity
Biological process: negative regulation of programmed cell death; proteolysis; amino acid metabolic process
Cellular component: extracellular exosome
Genetic constraint (gnomAD): Loss-of-function variants: 28 observed, 33.92 expected, observed/expected ratio (o/e) 0.83, 90% interval 0.61 to 1.13. The upper end of that interval is the gene's LOEUF score, 1.13, which puts it in group 4 of 6, group 1 being the genes least tolerant of losing a copy. Missense variants: 507 observed, 520.53 expected, observed/expected ratio (o/e) 0.97, 90% interval 0.9 to 1.05. Synonymous variants: 205 observed, 217.64 expected, observed/expected ratio (o/e) 0.94, 90% interval 0.84 to 1.06.
Gene-disease validity (ClinGen):
ClinGen rates the evidence that PEPD causes each of these diseases.
prolidase deficiency (autosomal recessive): Definitive. An inherited disorder of peptide metabolism characterized by severe skin lesions, recurrent infections (involving mainly the skin and respiratory system), dysmorphic facial features, variable cognitive impairment, and splenomegaly.
Homologues: Orthologues: chimpanzee PEPD (99% identical), macaque PEPD (97% identical), pig PEPD (92% identical), dog PEPD (92% identical), mouse Pepd (89% identical), guinea pig PEPD (88% identical), rat Pepd (87% identical), rabbit PEPD (82% identical), zebrafish pepd (74% identical), tropical clawed frog pepd (74% identical), Caenorhabditis elegans K12C11.1 (53% identical), Drosophila melanogaster Dip-C (51% identical). Paralogues in human: XPNPEP3 (27% identical), XPNPEP2 (18% identical), XPNPEP1 (18% identical), METAP1 (12% identical), METAP1D (12% identical), METAP2 (12% identical), PA2G4 (11% identical).
Diseases named in the same sentence as PEPD in open-access papers:
PEPD is named in the same sentence as 50 diseases in open-access papers, as found by Europe PMC text mining. Sharing a sentence is not in itself a finding about the gene and the disease. The quoted sentences say what the papers report.
type 2 diabetes (6 papers, 2013 to 2025). "Genetic polymorphisms in CDKAL1, CDKN2A/2B, KCNJ11, KCNQ1, and PEPD that we selected as potential effect modifiers were found to be associated with type 2 diabetes in the East Asian population." (PMID 32722593, 2020). "We did not detect statistically significant interactions between coffee consumption and five SNPs related to type 2 diabetes (CDKAL1 rs7756992, CDKN2A/B rs10811661, KCNJ11 rs5215, KCNQ1 rs163184, and PEPD rs3786897) in the association between coffee and the risk of type 2 diabetes." (PMID 32722593, 2020). "Many loci associated with adiponectin levels are shared with other insulin resistance traits and risk of type 2 diabetes, including loci near IRS1, LYPAL1, ARL15/FST, VEGFA, CMIP, and PEPD." (PMID 32915782, 2020). "We did not observe significant interactions by five single nucleotide polymorphisms (SNPs) related to type 2 diabetes (CDKAL1 rs7756992, CDKN2A/B rs10811661, KCNJ11 rs5215, KCNQ1 rs163184, and PEPD rs3786897) in the association between coffee and the risk of type 2 diabetes." (PMID 32722593, 2020). "Several type 2 diabetes mellitus (T2DM) susceptibility loci have been identified in or near GLIS3, PEPD, FITM2-R3HDML-HNF4A, KCNK16, MAEA, GCC1-PAX4, PSMD6, and ZFAND." (PMID 34822452, 2021).
breast carcinoma (5 papers, 2017 to 2025). "Cystatin-C (CST3) and Xaa-Pro dipeptidase (PEPD) were highly expressed in colon cancer samples compared to breast cancer." (PMID 41516087, 2025). "Moreover, differential expression of PEPD in two breast cancer cell lines, MCF-7 and MDA-MB-231, showed PEPD-dependent differences in HIF-1α levels." (PMID 40454316, 2025). "It explains the mechanism of pro-survival phenotype of MCF-7 cells and suggests that up-regulation of POX and down-regulation of PEPD may represent a novel strategy for breast cancer treatment." (PMID 34085157, 2021). "Indeed, a previous study found that PEPD protein expression is approximately 2-fold higher in breast cancer tissues than in normal breast tissues from untreated patients." (PMID 29233996, 2017). "The link between PEPD-PRODH/POX-proline-collagen biosynthesis axis and apoptosis mode may explain the mechanism underlying the chemopreventive activity of celecoxib in MCF-7 breast cancer cells." (PMID 34577574, 2021). "In MCF-7 breast cancer cells, Cx affected proline metabolism through upregulation of proline biosynthesis, PRODH/POX and PYCRs expressions, PEPD activity, and downregulation of collagen biosynthesis." (PMID 34577574, 2021).
prolidase deficiency (5 papers, 2019 to 2023). "Prolidase deficiency (PD) is a rare autosomal recessive inborn error of immunity caused by biallelic homozygous or compound heterozygous loss-of-function mutations in PEPD, the gene that encodes prolidase." (PMID 38088248, 2023). "Prolidase deficiency (PD) (OMIM170100) is an autosomal recessive inborn error of metabolism caused by mutations in the PEPD gene encoding the enzyme prolidase D, leading to defects in turnover of collagen and other proline-containing proteins." (PMID 35197125, 2022). "Prolidase deficiency (PD) is an autosomal recessive inborn multisystemic disease caused by mutations in the PEPD gene encoding the enzyme prolidase D, leading to defects in turnover of proline-containing proteins, such as collagen." (PMID 35197125, 2022). "Prolidase deficiency (PD) is a rare disorder caused by homozygous or compoundheterozygous variants in the PEPD gene (PeptidaseD, OMIM*613230)." (PMID 33877262, 2021). "Prolidase deficiency is a rare metabolic condition characterized by mutations in the PEPD gene resulting in disturbed collagene formation." (PMID 31799221, 2019). "Most publications concern prolidase deficiency—a genetic disease resulted from a decrease in or lack of PEPD activity." (PMID 32824561, 2020).
colon cancer (4 papers, 2017 to 2025).
cognitive decline (2 papers, 2022 to 2025). "Higher levels of NNT, MYO15A, and GCA were protective in females; greater expression of PEPD, CTNNBL1, MVB12A, XKR8, WBP1L, and GALNT7-DT were associated with faster cognitive decline in females." (PMID 40166028, 2025). "The bioinformatics data together indicate that upregulation of SERPINA1, VCP, PRNP, CIP2A, HSPA9, and UQCRC2 and downregulation of IGFBP3, CRHBP, PEPD, and GUSB were correlated to cognitive decline in T2DM patients." (PMID 36506101, 2022).
asthma (1 paper, 2011). "Finally, increased serum activity of PEPD has been associated with diseases such as asthma, coronary artery disease, and fatty liver disease." (PMID 21247474, 2011).
colitis (1 paper, 2017). Inflammation of the colon. "In conclusion, we have identified a possible new fecal marker of colitis; peptidase D. Future studies of its potential as a biomarker of IBD in humans are essential." (PMID 28323866, 2017). "The potential of peptidase D as a fecal marker of colitis needs to be confirmed by further studies in humans, which was beyond the scope of this study." (PMID 28323866, 2017).
colorectal cancer (1 paper, 2024). A primary or metastatic malignant neoplasm that affects the colon or rectum. "PEPD is a peptidase that has been shown to inhibit tumor signaling in colorectal cancer through promoting epidermal growth factor receptor inhibition." (PMID 38732562, 2024).
erythromelalgia (1 paper, 2015). A rare neurovascular peripheral pain disorder due to the intermittent blockage of the blood vessels, usually in the lower extremities or hands. "A differential effect of IEM and PEPD mutations on sympathetic ganglion neurons might contribute to the different pattern of vasomotor symptomology in patients with PEPD, compared to those with inherited erythromelalgia." (PMID 25957174, 2015).
Gastrointestinal hemorrhage (1 paper, 2017). Hemorrhage affecting the gastrointestinal tract. "Among them, rs7318369 in PEPD was associated with gastrointestinal hemorrhage." (PMID 28686612, 2017).
Granuloma (1 paper, 2014). A compact, organized collection of mature mononuclear phagocytes, which may be but is not necessarily accompanied by accessory features such as necrosis. "Our study showed that C4b, FN, and PEPD are associated with tissue damage, granuloma formation, and cavity formation, respectively, in patients with PTB." (PMID 24484408, 2014). "C4b may be associated with tissue damage, while FN and PEPD are associated with granuloma and cavity formation, respectively." (PMID 24484408, 2014).
keloid (1 paper, 2008). An irregularly shaped, elevated mark on the skin caused by deposits of excessive amounts of collagen during wound healing. "As a result, there were 25 known keloid-related genes reported among the analyzed genes, whereas two pairs of them (COL14A1 and TNC, COL1A2 and PEPD) were co-occurred in the literature that mentioned the curated keyword 'keloid' (data not shown)." (PMID 18620599, 2008).
liver cancer (1 paper, 2020). An epithelial or non-epithelial malignant neoplasm that arises from the liver. "At day 5, one (A1AG) of the upregulated proteins and four (ENOA, F16P1, PEPD and PRDX1) of the downregulated proteins were reported to be associated with liver cancer." (PMID 32095334, 2020). "At days 3 and 5, six proteins (LG3BP, A1AG, ENOA, F16P1, PEPD and PRDX1) were related to liver cancer and other diseases." (PMID 32095334, 2020).
lung carcinoma (1 paper, 2020). "The results suggested that PEPD, SLC15A1, and SLC5A3 were candidates for individual lethal genes specific to lung cancer, and pairs of CBS-SLC7A11, CBS-SLC3A2, CMPK1-PTDSS1, CMPK1-PLD2 were candidate synergistic lethal genes specific in the tumors." (PMID 32085724, 2020).
metabolic syndrome (1 paper, 2012). A cluster of metabolic risk factors for CARDIOVASCULAR DISEASES and TYPE 2 DIABETES MELLITUS. "Therefore, adiponectin risk alleles at ZNF664 and PEPD are of considerable interest since they impart deleterious changes on aspects of the metabolic syndrome (increased TC, TG, LDL-C and WHR and decreased HDL-C), but also act to decrease BMI and percent fat." (PMID 22479202, 2012).
Obesity (1 paper, 2015). Accumulation of substantial excess body fat. "Even though PEPD associations with T2D are ethnically heterogeneous, identification of a possible role of PEPD in susceptibility to T2D and obesity may provide crucial insights into biological mechanisms of these conditions." (PMID 26363598, 2015).
Sjögren’s syndrome (1 paper, 2023). "Here, we report a 28-year-old female with PD, displaying features of early-onset Sjögren’s syndrome (SjS) and vasculitis, due to a novel homozygous large deletion in PEPD." (PMID 38088248, 2023).
tumor (7 papers, 2017 to 2024). "Tumors grew rapidly on control siRNA, but PEPD siRNA caused progressive tumor regression; at the end of the experiment, average tumor size and tumor weight in the PEPD siRNA group were only 17.3% and 17.1% of that in the control siRNA group." (PMID 29233996, 2017). "Expression of PEPD was significantly higher in tumor tissue in comparison to control brain tissue (+43%, p < 0.0001)." (PMID 38275897, 2024). "Whereas tumors grew rapidly on scramble siRNA, PEPD siRNA inhibited tumor growth by 71.1% (tumor volume or tumor weight) at the end of the experiment." (PMID 34880421, 2021). "Therefore, expression of POX/PRODH, PYCR1, PYCR2, PYCR3, and PEPD was evaluated in both tumor and brain." (PMID 38275897, 2024). "In both brain and tumor samples, relative mRNA expression of key proline cycle enzymes, that is, POX/PRODH, PYCR1, PYCR2, and PYCR3, were evaluated, along with the expression of genes associated with ECM degradation, i.e., PEPD, MMP-2, and MMP-9." (PMID 38275897, 2024). "PEPD involvement in tumor growth, invasiveness, and spreading has been demonstrated." (PMID 38275897, 2024). "In addition, PEPD promotes apoptosis in tumor tissues through decreased expression of B-cell lymphoma 2 (BCL-2) and Bcl-2-associated X (BAX) as well as upregulated expression of caspase-3, -8, -9." (PMID 32824561, 2020). "Excess dietary iron in tumor tissues was also associated with significant changes (generally, increases; p ≤ 0.05) in proteins involved in modulating cell protein integrity (HSPA5, HSPA9, ITGB1, PSMA4, DPP7, and PEPD), cell mobility and growth (CAPZB), and immunologic factors (FCGBP)." (PMID 38732562, 2024). "However, recombinant human PEPD or an enzymatically inactive mutant, when added to cell culture or injected to tumor-bearing mice (with inhibition of the plasma proteolysis pathway), strongly inhibits the growth of cancer cells overexpressing ErbB1 and/or ErbB29,10,12." (PMID 29233996, 2017). "In the extracellular domain, PEPD and “upstream” metalloproteinases (MMP-2 and -9) have been shown to influence tumor metabolism and to shape microenvironment–tumor interplay." (PMID 38275897, 2024). "We noticed the activation of the proline cycle (↑ PEPD, POX/PRODH and PYCR1) to indicate constant remodeling (synthesis and degradation) of matrix collagen, which in turn can contribute to tumor heterogeneity." (PMID 38397798, 2024). "The percentage of cells with strong positive staining was significantly higher for tumor tissue when treated with PYCR1, PEPD, and MMP-9 antibodies (p < 0.0001) and lower when treated with POX/PRODH (p < 0.0001)." (PMID 38275897, 2024).
cancer (5 papers, 2016 to 2025). A tumor composed of atypical neoplastic, often pleomorphic cells that invade other tissues. "Given that hPEPD-G278D is a human protein and is unlikely to interfere with the enzymatic function of endogenous PEPD in normal cells, it is a highly promising agent for combating ErbB2-overexpressing cancer." (PMID 27286447, 2016). "Agents that down regulate PEPD may be promising cancer therapeutic agents." (PMID 29233996, 2017). "Thus, recombinant PEPD or its mutant is a promising cancer therapeutic." (PMID 29233996, 2017).
infection (2 papers, 2009 to 2022). The state of being infected such as from the introduction of a foreign agent such as serum, vaccine, antigenic substance or organism. "PD patients lack PEPD activity, leading to inhibition of type I IFN receptor-dependent immune responses, which are critical for the amplification of innate immunity and the mobilization of adaptive immunity in response to infection." (PMID 35197125, 2022).
metabolic disease (1 paper, 2020). A congenital disorder (due to inherited enzyme abnormality) or acquired (due to failure of a metabolically important organ) disorder resulting from an abnormal metabolic process. "They enabled the detection of several genetic variants of PEPD that may be associated with the development of metabolic diseases." (PMID 32824561, 2020).
PEPD also shares sentences with these, for which no sentence is quoted: neurodegenerative disease (4 papers); amyotrophic lateral sclerosis (2); connective tissue disease (2); Insulin resistance (2); prion disease (2); scrapie (2); Skin ulcer (2); Alzheimer disease (1); Ataxia (1); autoimmune disease (1); Autoimmunity (1); bladder cancer (1); brain diseases (1); coronary artery disease (1); diabetes (1); falciparum malaria (1); fatal familial insomnia (1); fatty liver disease (1); Fronto-Temporal Dementia (1); Huntington disease (1); inflammatory bowel disease (1); liver disease (1); neuroblastoma (1); neurological disorders (1); Parkinson disease (1); pregnancy-induced hypertension (1); respiratory infection (1); systemic lupus erythematosus (1); tick-borne encephalitis (1).